SOX9 (SRY-box transcription factor 9)
Diseases named in the same sentence as SOX9 in open-access papers (continued):
Sharing a sentence is not in itself a finding about the gene and the disease.
cancer (continued). "The upregulation of SOX9 expression reduces the expression of E-cadherin and increases the expression of vimentin and α-SMA, thereby promoting the invasion and metastasis of cancer cells and decreasing the survival of patients with CCA by conferring chemoresistance." (PMID 36300097, 2022). "Furthermore, CPX exposure significantly decreased spheroid formation and cancer stem cell marker proteins (CD44 and SOX9), suggesting that CPX acts, at least in part, through effects on CSCs." (PMID 34059639, 2021). "Sex-Determining Region Y-Box 9 Protein (SOX9) has been shown to inhibit differentiation of EpSCs into keratinocytes by stimulating symmetric cell division (SCD) during stem cell self-renewal and cancer progression." (PMID 34361001, 2021). "To identify a cancer stem-cell-like subpopulation in MDA-MB-231 spheroid cells, we included stem cell markers, such as CD133, CD90, CD44, and CD24, and stem cell transcription factors such as SOX9 and Nanog." (PMID 34831064, 2021). "As demonstrated in the top DEGs, specifically cancer stem lineage clusters expressed high levels of stemness feature genes including ALDH1A1, PROM1, and NES, while ductal lineage cluster expressed high levels of ductal markers such as MMP7, TSPAN8, and SOX9." (PMID 34732701, 2021). "Both HS578T-Hyg and MDA-MB-435-Hyg cancer cells co-expressed Snail and Slug, but lacked Sox9 expression." (PMID 32430004, 2020). "We find that CDKL5 is widely expressed in cancer cell lines, raising the possibility that CDKL5 might regulate SOX9 function in cancer cells." (PMID 32317630, 2020). "Recently, several reports (prevalently microRNA studies) have indicated that the elevated expression of RUNX2 or SOX9 conferred resistance to taxanes (prevalently docetaxel) and CDDP in prostate, gastric, lung, breast, and ovarian cancer cells and tissues." (PMID 33287223, 2020). "Although this resemblance served the purpose of properly separating cancer cell types, mesenchymal cancer cells lack expression of important tRG genes such as AQP4, FAM107A, SOX9, and GLI3, and tRG lack the expression of mesenchymal genes such as CD44 and TIMP1." (PMID 32641768, 2020). "Since SOX9+/HNF4α+ HybHPs was regenerated in the injured liver without developing into cancer, we focused on the Hoxb6 effects on the HybHPs." (PMID 32763157, 2020). "Collectively, these findings suggest that manipulation of SOX9 to impede NSCLC metastasis and malignancy may be clinically useful and provide a new insight for the intervention of distal metastasis in cancer therapy." (PMID 31060551, 2019). "Therefore, more work is needed to study SOX9 participation in Wnt/β-catenin and other pathways, including its relationship with other TFs related with stem-cell maintenance in different types of cancer, in order to elucidate additional mechanisms through which it may function." (PMID 31057614, 2019). "In our models, Napabucasin treatment similarly reduced the stemness property of lung colonizing cancer cells, illustrated by a significant decrease in the expression of stemness genes, e.g. CK14, SOX5, SOX9, and HOXA4, and an increased expression of the differentiated cell marker, CK18." (PMID 31086186, 2019). "Moreover, cancer stemness related genes such as CD44, CD133, LGR5, LSD1, OCT4, Sox2 and Sox9 were co-upregulated with LETM1 in A549 cells." (PMID 31500591, 2019). "Expressions of SOX9 and CK19 in cancer cells were heterogeneous." (PMID 30420613, 2018). "SOX9 (sex-determining region Y (SRY)-box9 protein), a transcription factor expressed in most solid tumors, is reported as a key regulator involved in maintaining cancer hallmarks including the GSCs state." (PMID 29416606, 2018). "Given that there are multiple growth factors and proliferative signals governing cancer cell expansion in patients with iCCA, it is not surprising that low levels of SOX9 expression alone does not have a significant impact on the proliferation of cancer cells." (PMID 30420613, 2018).
cancer (continued). "Accordingly, embryonic stem cells and cancer cells have been reported to share a common gene expression pattern, and the expression of ESC markers (such as HMGA2, KLF4, NOTCH1, OCT3/4 and SOX9) that are known to play a key role in pluripotency, self-renewal, and cancer, is increased in many tumors." (PMID 29383160, 2017). "One of the target genes of SOX9 is ETV5, an effector of EMT and a metastatic target in cancer." (PMID 28272374, 2017). "Because SOX9 and SLUG are the determinants of a mammary (cancer) stem cell state, these findings may suggest that M13HS hybrid cell clones putatively exhibit CS/IC properties." (PMID 28768501, 2017). "Increases in expression of the progenitor cell markers SOX2, SOX9 and NANOG in A549 cells seen in the present study could be indicative of the presence of such a cancer stem cell population." (PMID 27792742, 2016). "This analysis, which was limited to the subset of ERG-positive and PTEN-deleted cancers where SOX9 had strongest prognostic impact in univariate analysis, revealed that the prognostic value of SOX9 was not independent from the established prognosticators." (PMID 26030748, 2015). "While no unequivocal changes in the SOX9 expression levels were found in different stages of ERG-negative cancers, a gradual decrease of SOX9 paralleled progression to advanced stage, high Gleason grade, metastatic growth, and presence of PTEN deletions in ERG-positive cancers (p<0.0001 each)." (PMID 26030748, 2015). "Absent or reduced SOX9 expression was strongly linked to biochemical (PSA) recurrence in the subset of ERG-positive cancers (p<0.0001), but not in ERG-negative cancers (p = 0.80)." (PMID 26030748, 2015). "Because SOX9 expression was linked to the PTEN status, we also compared the prognostic impact of SOX9 in cancers with and without PTEN deletions." (PMID 26030748, 2015). "Many of those more frequent in BRAFmut/MSS cancers, for example deletions at 6p25.1-6p21.33 and at specific loci on 17q where several Wnt regulatory genes reside (RNF43, AXIN2 and SOX9), have not commonly been associated with CRC." (PMID 24651849, 2014). "It is well-accepted that genes regulating development also play critical roles in cancer development and progression, and thus it is not surprising that Sox9 expression is dysregulated in cancer." (PMID 25004243, 2014). "Indeed, several of the 15 synergistic DEGs we validated are directly or indirectly associated with acquisition of stem-like phenotypes in normal or cancer cells, particularly SNAI1, SOX9 and GBX2." (PMID 25401416, 2014). "In addition, other (cancer) ‘stemness’ genes (like LGR4, SOX9, KLF5 and MET) are also upregulated in the pSP." (PMID 24069258, 2013). "In sum, the (early) absence of Sox9 expression in the prostate prevents progression to mPIN and cancer in the TRAMP model." (PMID 22761195, 2012). "Consistent with this requirement for Sox9 during cancer initiation, deletion of Sox9 after the mPIN stage did not prevent TRAMP grafts from developing into aggressive tumors." (PMID 22761195, 2012). "Upregulation in cancers was seen in TWISTNB 4, YPEL2 3, CBX3 3, SOX9 8 and β-catenin 7, while downregulation was seen in TWISTNB 6, YPEL2 1, YPEL5 3, SEPT4 2, SEPT6 4, CBX3 3, SOX9 2 and β-catenin 2, compared with those in normal mucosa." (PMID 16504081, 2006). "Interestingly, the FT190 cells displayed no such advantage, suggesting that SOX9 only has this effect in a cancer cell context." (PMID 41031891, 2025). "Similarly, cancer cells showed heterogeneously high expression of SOX9, which was irrespective of the presence of wild-type cells." (PMID 38706869, 2024).
cancer (continued). "Further analyzing the prognostic values for SOX9 expression in cancer individuals revealed that OS is long in ACC and short in LGG, CESC, and THYM, suggesting that high SOX9 expression is positively correlated with the worst OS in LGG, CESC, and THYM, which could be used as a prognostic maker." (PMID 37020558, 2023). "On the contrary, SOX9, SOX10, and SOX11 are upregulated in basal-like BC, indicating that therapeutic strategies targeting these factors may be beneficial for this subtype of cancer, which currently lacks targeted therapy." (PMID 37444447, 2023). "Further analysis of the prognostic value of SOX9 expression in individuals with cancer revealed that overall survival was longer in ACC (adrenocortical carcinoma) and shorter in LGG, CESC, and THYM when SOX9 was highly expressed in pan-cancer compared with the matched healthy tissues." (PMID 37020558, 2023). "Key genes that contribute to gliogenesis but also contribute to the stemness in GBM: Notch (cancer stem cells), Sox9, Sox4, and SHH.Notch signaling pathway: In gliogenesis, Notch effector protein (NIFA) binds to GFAP promotor and contributes to astrocytogenesis." (PMID 35538578, 2022). "However, most epigenetic studies of SOX9/Sox9 have been in cancer tissues, rather than during organogenesis." (PMID 36114905, 2022). "Interestingly, SNAI1-KO cells presented higher stem cell frequency and underwent a switch in the expression of cancer stemness signaling genes, with significant upregulation of epithelial KIT, ALDH1A1 and SOX2, and analogous downregulation of mesenchymal CD44 and SOX9." (PMID 36171192, 2022). "Notably, the expression levels of normal pancreatic epithelial cell markers, SST and INS, were specifically higher compared to cancer cells, suggesting the normal functions of these cells, while malignant marker genes, SOX9 and KRT18, were remarkably upregulated in cancer cells." (PMID 35941362, 2022). "Interestingly, unlike the nuclear localization of transcription factor SOX9 protein in other types of cancer tissues, we observed the preferential cytoplasmic localization of SOX9 protein in HGOC." (PMID 35159173, 2022). "This could be due to Sox9 was already expressed at high levels in primary cancer tissues, and thus the difference was not obvious." (PMID 34281572, 2021). "In order to validate the hypothesis that THY1 is related to cancer stemness and immunotherapy resistance, we performed IHC staining on six tissue samples of LUAD patients who received at least three cycles of PD-1 mAb treatments using THY1 and SOX9 antibodies." (PMID 35071018, 2021). "Moreover, the data demonstrated a strikingly poor disease outcome in a subgroup of 101 patients with ERG positive, PTEN deleted cancers with absent SOX9 expression." (PMID 26030748, 2015). "In order to determine whether SOX9 interaction with NF-Y could be limited to cancer cells, and not in normal intestinal epithelium, SOX9 ChIP-seq on normal intestinal epithelial cells should be performed." (PMID 26040697, 2015). "SOX9 expression levels were comparable in luminal cells of normal prostate glands (50% SOX9 positive) and 3,671 cancers lacking TMPRSS2:ERG fusion (55% SOX9 positive), but was markedly increased in 3,116 ERG-fusion positive cancers (81% SOX9 positive, p<0.0001)." (PMID 26030748, 2015). "Since it is well recognized that genes and pathways critical for development may also play important roles in cancer development and progression, it is not surprising that SOX9 is involved in cancers." (PMID 24188461, 2013). "In addition, we detected some other ‘cancer stemness’ markers (e.g. LGR4, SOX9, KLF5, MET) as well as pancreatic embryogenesis-related factors which may be re-initiated in CSC (e.g. HNF4A)." (PMID 24069258, 2013). "However, Sox9-positive cells did not exhibit increased levels of the cancer stemness marker CD44." (PMID 39518936, 2024).
cancer (continued). "Additionally, SLUG has been shown to directly interact with SOX9 to promote the formation of cancer stem-like cells in lung cancer, and there is the recent speculation that TUBB3 may be playing a role in the maintenance of cancer stem like cells." (PMID 35573698, 2022). "Indeed, Sox9 expression was increased in the examined cancer cell lines (data not shown)." (PMID 25955804, 2015). "It is noteworthy that many known genes in cancer, e.g., HIF1A, SLC16A3, EPCAM, and SOX9, were consistent, albeit in fewer datasets and so did not meet our inclusion criteria." (PMID 39774001, 2025). "All tuft cell-like cancers identified in this way also strongly expressed other tuft cell-markers, such as TRPM5, SOX9, ASCL2, and AVIL but not CHAT." (PMID 36402755, 2022). "Of the top 20 genes in TCGA or MSKCC, AMER1, SOX9, ARID1A and TCF7L2 were not included in our cancer panel." (PMID 34074070, 2021). "For example, the prognostic impact of SOX9, SENP1 and mTOR was limited to ERG positive cancers while FOXA1, MTCO2 and FOXP2 were only prognostic in ERG negative cancers." (PMID 31606028, 2019). "In earlier studies we had described several molecular features that were either prognostic in ERG positive (for example, SOX9, and SENP1 or in ERG negative cancers (for example, GGH and NBS1) but not in both groups." (PMID 31043167, 2019). "However, the inverse association between loss of SOX9 overexpression and PTEN deletion found in ERG-positive cancers indicates that very high SOX9 protein levels—as induced by ERG-fusion—might not per se provide a selection advantage to PTEN-deleted cancer cells." (PMID 26030748, 2015). "Overall, the significant over-expression of stem cell markers SOX2, OCT4, SOX9 and CD44 suggests that the cells present in spherical aggregates are CSC-like whereas the non-spherogenic, adherent layer of cells are non-CSC cancer cells." (PMID 24423398, 2013). "To characterize the CSC-like cells (cells present in the sphere-like aggregates), we compared the expression levels of CD44, OCT-4, SOX2 and SOX9 between CSC-like (spherogenic) and non-CSC (non-spherogenic) UM1 cancer cells with Western blotting." (PMID 24423398, 2013). "It is the PI3K-Pdk1 pathway, but not Akt or Erk what increases the survival of more stem-like cells with higher levels of the stem and cancer markers Sca-1, CD44 and Sox9, in absence of p38 activity." (PMID 24265727, 2013). "Conversely, ETV5 and SOX9 were not affected by AR-V7 knockdown in CWR-R1 and 22Rv1 cancer cells." (PMID 29069764, 2017). "In addition, DENSpm-treated cells exhibited elevated levels of expression of several key stem cell markers including POU5F1, Sox9, CD44, BMI1, and Lin28B, although other transcripts that are found in liver stem and cancer stem cells remained absent (PROM1, CD133)." (PMID 30567412, 2018).
infection (39 papers, 2011 to 2026). The state of being infected such as from the introduction of a foreign agent such as serum, vaccine, antigenic substance or organism. "(H) Quantification of EdU+Sox9 + cells per 250 μm high infection areas in retinas injected with CCA at indicated ages: P6 (n=13), P28 (n=17), and P255-P347 (n=7)." (PMID 40178080, 2025). "Taken together, our data indicates that infection with Chlamydia induces AP activity and changes in the expression of various MSCs markers including the increase in Sox9 level in infected cells." (PMID 39467689, 2024). "Infection of Irgm1 knockdown lentivirus significantly upregulated the transcription of Wnt target genes (Lgr5 and Sox9) and Wnt luciferase activity in a dose-dependent manner." (PMID 35197566, 2022). "First, we confirmed that at 7 days after AAV8-TBG-GFP infection, SOX9+ LPCs were GFP−, while hepatocytes (SOX9−) expressed GFP in autophagy-deficient livers, confirming that ductular LPCs are not expressing GFP following AAV8-TBG-GFP infection." (PMID 34088666, 2021). "The co-localization of ACE2, LUC (Luciferase), and SOX9 indicated the successful infection of SARS-CoV-2 in ACE2+/SOX9+ progenitor of lung." (PMID 33500718, 2021). "The result showed that the expression of Sox9 in BMSCs was significantly decreased after infection with sg126-expressing lentivirus." (PMID 32763157, 2020). "The infected mice exhibited increased mRNA levels of canonical (Wnt1, Wnt2, Wnt3, and Wnt3a) and noncanonical (Wnt5a) Wnt molecules, receptors (Fz1 and Fz5) and the Wnt signalling target gene Sox9 in hepatocytes at 6 and 12 weeks post-infection." (PMID 28331224, 2017). "Infecting the cells with a 50- or 200-multiplicity of infection (moi) reduced the SOX9 protein level to <50% or <10% of its initial levels in cells infected with 50- or 200-moi of Ad-CMV-Null, respectively." (PMID 27436052, 2016). "Analysis of RNA-Seq data indicated that, when the levels of Sox9 mRNA were decreased more than 8-fold by infection with Ad-CMV-Cre, 196 genes showed a decrease in expression of at least 4-fold." (PMID 25229425, 2014). "Infection of primary cultured chondrocytes with adenoviruses expressing Sox9, followed by promotion of synthesis of cartilage matrix proteins, including Col2, caused ER stress." (PMID 24711445, 2014). "In ATDC5 cells (murine chondrogenic cells) transfected with 2.0 kb-Luc or 1.0 kb-Luc constructs, reporter activities were dramatically induced by infection of adenoviruses expressing Sox9." (PMID 24711445, 2014). "Expression of Sox9 after infection was evaluated by western blot technique on day 2, day 5, and day 7 after incubation in a normal medium without any supplemented growth factors in micromass cultue." (PMID 24551211, 2014). "Gene knockdown was achieved by infecting primary cultures isolated from Sox9fl/fl mice with adenovirus (AdV) producing Cre recombinase (AdV-Cre), while infection with AdV containing full length murine Sox9 (AdV-Sox9), served as an overexpression model." (PMID 22046352, 2011). "Compared to AdV-GFP controls, AdV-Cre and AdV-shSpp1 infection led to successful targeted knockdown of Sox9 and Spp1 respectively." (PMID 22046352, 2011). "Given that chondrocyte dedifferentiation, which is marked by the loss of anabolic factor expression, leads to chondrocyte senescence, we also assessed the mRNA expression levels of the major anabolic factors, Col2a1, Acan, and Sox9, and found that they were decreased by Ad‐Zmiz1 infection." (PMID 40040621, 2025). "Our data show that SOX9 is expressed progressively during infection in multiple liver cell types, most extensively in injured hepatocytes adjacent to scarring, highlighting additional cell specific roles identified for SOX9 in the context of injury and parenchymal repair." (PMID 40489560, 2025).